CRP (C-reactive protein)
Diseases named in the same sentence as CRP in open-access papers (continued):
Sharing a sentence is not in itself a finding about the gene and the disease.
cancer (continued). "Plasma YKL-40 is an acute-phase protein like serum CRP but in contrast to CRP YKL-40 is produced locally in areas with inflammation by cancer cells, macrophages, and leucocytes." (PMID 24498368, 2014). "Some studies have been conducted to determine if elevated CRP levels and cancer are directly related." (PMID 24800842, 2014). "In most prevalent studies, serum CRP levels have been demonstrated to be highly elevated in cancer patients compared to healthy individuals." (PMID 24800842, 2014). "Elevated circulating levels of inflammatory biomarkers, i.e., IL6, TNFα, C-reactive protein (CRP), have been associated with a greater risk for several types of cancer and cancer prognosis, including breast." (PMID 23991131, 2013). "The Glasgow Prognostic Score (GPS) is a combined score of elevated CRP (>10 mg/L) and low albumin (<35 g/L) and has been demonstrated as a predictive test for poor outcomes in a variety of cancers." (PMID 23819063, 2013). "The levels for CRP were also significantly reduced in RM samples as compared to active cancer and returned to almost normal levels." (PMID 24244307, 2013). "The overproduction of selective cytokines such as interleukin-6, tumor necrosis factor α, and CRP has been shown to play a key role in inducing chronic inflammation in cancer patients." (PMID 24244659, 2013). "In the subgroup of patients without metastasis at the time of penile surgery, however, both advanced tumor stage and an elevated CRP value were identified as independent predictors of poor cancer specific survival." (PMID 23642165, 2013). "Because radiation increased CRP in anemic cancer patients, CRP in serum was measured in irradiated mice." (PMID 24175013, 2013). "The usefulness of the serum levels of CRP in the early diagnosis and in the monitoring of the course of bacterial infections in febrile neutropenic patients with cancer was also evaluated in the present study." (PMID 23634180, 2013). "ALP is also considered an inflammatory marker in cancer patients, and its elevation correlates with other inflammatory markers such as high C-reactive protein, low blood zinc levels, and reduction in overall survival of cancer patients." (PMID 23653670, 2013). "The same results were also reported in the Glasgow Prognostic Score (GPS) system, a prognosis model based on CRP and albumin, which can effectively predict the treatment outcome of various cancers." (PMID 24130817, 2013). "Accumulating evidence indicates that components of the systemic inflammatory response, such as C-reactive protein (CRP) and neutrophil-to-lymphocyte ratio (NLR), have been associated with prognosis of various cancers." (PMID 23409924, 2013). "Same group in a recent study assessing the outcome of the modified GPS in a lager cohort (n = 8759) reported that 90% of cancer patients with a low albumin level had an elevated CRP." (PMID 23590192, 2013). "Several mechanisms of increased CRP levels in malignant tumors are now known due to various therories." (PMID 24255664, 2013). "Based on Cox’s univariate proportional hazard model, LNR >0.15 (p=0.033), CEA >6 (p=0.01) and CRP positivity (p=0.008) were significant prognostic factors for poor cancer-specific survival." (PMID 23833661, 2013). "Eleven proteins were significantly different between RM and HC, while 2 proteins (CA125 and CRP) showed significant differences between RM and active cancer." (PMID 24244307, 2013). "Several large trials among healthy individuals or cancer survivors reported that exercise including resistance training can lead to a reduction of markers of inflammation such as C-reactive protein (CRP)." (PMID 23537231, 2013). "The Kaplan-Meier 5-year cancer-specific survival (CSS) rate was 38.9% for patients with preoperative CRP levels above 15 mg/l and 84.3% for those with lower levels (p=0.001)." (PMID 23642165, 2013).
cancer (continued). "On the other hand, the association between resistin plasma level, independent from BMI, and CRP (C - reactive protein) as an inflammatory phase protein factor in inflammatory related disorders including cancers especially CRC has been widely reported." (PMID 24551805, 2013). "Cancer patients, for whom plasma ascorbate concentration data before and after treatment were available, along with C-reactive protein (CRP) measurements, were chosen for analysis." (PMID 23947403, 2013). "Alternatively, CRP is a component of the acute- phase response mainly induced by interleukin-6, and thus has the potential to enhance or inhibit the proliferation of carcinoma cells." (PMID 23497335, 2013). "YKL-40 is a newly discovered plasma protein that – like CRP – is elevated during inflammatory conditions and cancer." (PMID 22095223, 2012). "Applying receiver-operating characteristic analyses, the CRP value exhibited an AUC (95% CI) of 0.78 (0.75 – 0.81; p < 0.001) for cancer specific and of 0.74 (0.71-0.78; p < 0.001) for overall survival." (PMID 22958305, 2012). "For some of these subjects, blood chemistry data before, during, and after IVC treatments provide measurements of plasma ascorbate, CRP levels, and the levels of cancer markers such as PSA and CEA." (PMID 22963460, 2012). "The high dose intravenous ascorbic acid therapy affects C-reactive protein levels and pro-inflammation cytokines in cancer patients." (PMID 22963460, 2012). "Median CRP and albumin measured in the normal and abnormal groups were both within normal ranges and the distribution of cancer types was broadly similar." (PMID 22588559, 2012). "Inflammation and elevated C-reactive protein (CRP) are associated with poor prognosis and decreased survival in many types of cancer." (PMID 22963460, 2012). "The cumulative incidence of any cancer as a function of age increased with increasing levels of CRP and YKL-40 (log-rank, P<0.001)." (PMID 22095223, 2012). "A score based on serum concentrations of C-reactive protein (CRP), albumin, gamma-glutamyl transferase (GGT), and HDL cholesterol was positively associated with death from cancer, circulatory disease, and all-cause mortality." (PMID 23092358, 2012). "All studies determined circulating CRP concentration before cancer diagnosis as a single measurement in time." (PMID 22912790, 2012). "Maximising both sensitivity and specificity for prediction of any cancer, a cut-point of 1.9 mg /l−1 was identified for levels of CRP (sensitivity and specificity both 57%) and of 62.0 μg l−1 for levels of YKL-40 (sensitivity and specificity both 59%)." (PMID 22095223, 2012). "Adiponectin, C-Reactive Protein, and Leptin are key components of the chronic inflammatory environment that have been associated with elevated SUA levels and cancer." (PMID 23369448, 2012). "The multifactorially adjusted HR of any cancer for a doubling of CRP levels was 1.15 (95% CI: 1.07–1.24), while further adjustment for YKL-40 levels resulted in a similar HR of 1.14 (1.05–1.23) (likelihood ratio test between models, P=0.26)." (PMID 22095223, 2012). "For CRP, median serum level was 3,366 ng/mL in early stage and 4,380 ng/mL in late stage carcinomas (P > 0.05)." (PMID 22954206, 2012). "There is increasing evidence that the presence of a systemic inflammatory response, as evidenced by elevated concentrations of CRP, is a prognostic factor in patients with advanced cancer." (PMID 22103888, 2011). "Patients (n=21 669) who had an incidental blood sample taken between 2000 and 2006 for C-reactive protein, albumin and calcium (and liver function tests where available) and a diagnosis of cancer were identified." (PMID 21266974, 2011). "A low albumin, an elevated mGPS, C-reactive protein, adjusted calcium, bilirubin, Alk phos, AST, ALT and GGT were associated with a reduced 5-year overall and cancer-specific survival (all P<0.001)." (PMID 21266974, 2011).
cancer (continued). "The Glasgow prognostic score (GPS) was introduced as a useful predictor for survival in patients with cancer by Forrest in 2003, and consists of the combination of 2 values, CRP and albumin." (PMID 22103888, 2011). "Some authors have observed an association between elevated serum C-reactive protein (CRP) levels and some cancers, like colorectal, lung and head and neck." (PMID 21352591, 2011). "In Cox multivariate regression analysis, the relationship between a mGPS of 2 and cancer-specific survival (hazard ratio (HR): 3.01, P<0.001) was stronger than that between C-reactive protein alone and cancer-specific survival (HR: 2.29, P<0.001)." (PMID 21266974, 2011). "A majority of the published cancer prognostic studies dichotomise CRP at 10 mg l–1, and the Glasgow Prognostic Score uses the same cut-off." (PMID 20234363, 2010). "C-reactive protein (CRP), a representative marker for inflammation, is known for its association with disease progression in many cancer types." (PMID 20465852, 2010). "There were higher circulating concentrations of C-reactive protein and lower albumin levels (and thus a higher proportion of mGPS 1 or 2), in those patients with cancer (all P<0.001)." (PMID 20717110, 2010). "When these biochemical parameters, together with bilirubin and ALT, were regressed against the presence of cancer, C-reactive protein, albumin, adjusted calcium, Alk phos and GGT were all shown to be independently associated with the presence of cancer." (PMID 20717110, 2010). "Although the involvement of midkine in inflammation is well-documented, only a weak correlation between midkine and CRP in cancer patients has been reported." (PMID 20920199, 2010). "In particular, C-reactive protein was associated with albumin and Alk phos and GGT associated with AST and ALT in both cancer and non-cancer cohorts." (PMID 20717110, 2010). "Patients with cancer had higher C-reactive protein and lower albumin levels (and thus a higher mGPS), higher adjusted calcium, Alk phos and GGT levels, but lower aspartate transaminase (AST) and alanine transaminase (ALT) levels (all P<0.001)." (PMID 20717110, 2010). "Rivory and colleagues demonstrated that cancer patients with elevated acute phase proteins, including CRP and alpha-1 acid glycoprotein (AAGP), had reduced CYP3A4 function as determined by the erythromycin breath test." (PMID 19450285, 2009). "In particular, as compared with another study concerning the relationship between CRP levels and cancer prognosis, a small number of advanced-stage patients were enrolled in this study." (PMID 19457231, 2009). "In reality, however, the CRP curve appears to be repeating as the immune system responds to the cancer in-vivo." (PMID 19948067, 2009). "Usually, static sampling of CRP has been used for clinical studies and these can predict disease presence or recurrence, notably for a number of cancers." (PMID 19948067, 2009). "Many studies have examined CRP levels in cancer patients compared with healthy controls and have identified a relationship between raised CRP and disease state." (PMID 19732183, 2009). "We have used frequent serial L-CRP measurements across three clinical laboratories in two countries and for different advanced cancers, and have demonstrated similar, repeatable observations of a cyclical variation in CRP levels in these patients." (PMID 19948067, 2009). "This concept is supported by data which demonstrated that reductions in CYP3A4 activity in patients with advanced cancer were correlated with increased plasma concentrations of IL-6 and CRP." (PMID 19450285, 2009). "Several studies regarding the role of preoperative CRP as a predictive indicator for the malignant potential and prognosis in various other cancers have been published." (PMID 16969356, 2006).
cancer (continued). "The aim of the present study was to examine the relationship between clinico-pathological status, preoperative C-reactive protein concentration and cancer-specific survival in patients undergoing resection for gastro-oesophageal cancer." (PMID 16685271, 2006). "An APPR has been well documented among patients with cancer, including gastric and oesophageal malignancies, and an elevated serum CRP has been identified as an adverse prognostic indicator, independent of stage of disease, among these patients." (PMID 17088911, 2006). "Inflammatory proteins, such as IL-6 or CRP, are reported to be higher in cancer patients compared to non-cancer patients." (PMID 16740157, 2006). "There is also evidence that C-reactive protein has independent prognostic value in primary operable cancer." (PMID 17024120, 2006). "On univariate survival analysis, sex (P=0.050), tumour stage (P⩽0.001), Fuhrman grade (P<0.001), UISS (P<0.001) and C-reactive protein (P<0.01) were significant predictors of cancer-specific survival." (PMID 16523196, 2006). "It was of interest that C-reactive protein (a systemic inflammatory response) was superior to tumour T-lymphocytic infiltration (a local inflammatory response) in predicting cancer specific survival." (PMID 15700032, 2005). "On univariate analysis, both C-reactive protein concentrations (P<0.001) and percentage tumour volume of CD4+ (P<0.05) T-lymphocytes were associated with cancer-specific survival." (PMID 15700032, 2005). "The aim of the present study was to examine the relationship between stage, grade, C-reactive protein and cancer-specific survival in patients with superficial or invasive bladder cancer." (PMID 15726119, 2005). "We sought to determine prospective measurements of body mass and composition, resting energy expenditure, energy and protein intake, and C-reactive protein over a course of chemotherapy in 82 patients with advanced cancer." (PMID 15726121, 2005). "In cancer, the factors which determine circulating concentrations of C-reactive protein are less clear, since studies in cell lines and animal tumour models have demonstrated that a number of factors stimulate C-reactive protein production." (PMID 15505624, 2004). "BMI and albumin were lower (P<0.05) and white cell count (P<0.001) and C-reactive protein (P<0.001) were higher in cancer patients compared with controls." (PMID 15570310, 2004). "Cancer-specific survival in patients with Dukes' B tumours and an elevated C-reactive protein concentration was similar to that of patients with Dukes' C tumours and a normal C-reactive protein concentration." (PMID 15150596, 2004). "In the cancer patients who had detectable C-reactive protein concentrations (n=41), the relationship between log10 C-reactive protein, log10IL-6, and log10IL-1Ra was examined in multiple linear regression analysis." (PMID 15570310, 2004). "The value of the present study is that it clearly identifies IL-6 from other candidate mediators of the increase in C-reactive protein concentration in a homogenuous cohort of cancer patients." (PMID 15570310, 2004). "The cancer-specific survival rates at 3 years for patients with a C-reactive protein ⩽10/>10 mgl−1 were 24 and 5%, respectively." (PMID 15354220, 2004). "In the cancer patients, there was a significant increase in both interleukin-6 and C-reactive protein concentration with increasing tumour grade." (PMID 15505624, 2004). "In the present study, when C-reactive protein concentrations were combined with Dukes' stage to form a new prognostic score, the combined score improved the prediction of cancer-specific survival." (PMID 15150596, 2004). "Cancer patients with elevated C-reactive protein concentrations had greater concentrations of interleukin-6 (P<0.01) and interleukin-1 receptor antagonist (P<0.05)." (PMID 15570310, 2004).
cancer (continued). "Cancer-specific survival at 3 years ranged from 100% in patients with Dukes' B tumours and a normal C-reactive protein concentration to 40% in patients with Dukes' C tumours and an elevated C-reactive protein concentration." (PMID 15150596, 2004). "Weight-losing patients had a lower vitamin C (P < 0.05) and thiamine (P < 0.002) intake, and a higher elevation in plasma C-reactive protein and a lower prealbumin level (P < 0.02), when compared to both weight-stable cancer patients and controls." (PMID 8260373, 1993). "Tandem alterations in albumin and CRP levels can bolster clinical diagnosis of inflammation and support the predictive power of acute‐phase reactants in the identification of depressive symptoms among cancer patients." (PMID 40851223, 2026). "One meta-analysis of 26 RCTs varying from durations of 8–104 weeks and offering structured exercise interventions for cancer survivors investigated exercise’s effect on cytokine levels, including CRP and TNF-α, and showed decreased pro-inflammatory markers with exercise across all cancer types." (PMID 41546786, 2026). "CRP is a widely used marker of inflammation that is increased in many cancer types, including PCa." (PMID 41546786, 2026). "Numerous immune and inflammatory markers—including the neutrophil-to-lymphocyte ratio (NLR), platelet-to-lymphocyte ratio (PLR), lymphocyte-to-CRP ratio, lymphocyte-to-monocyte ratio, and CRP-to-albumin ratio—have been shown to provide prognostic value in cancer patients." (PMID 40836295, 2025). "In addition to these decreases, CRP levels showed a highly significant increase (P = 0.0014**), suggesting an inflammatory response related to cancer." (PMID 40315194, 2025). "Higher values of NLR are associated with greater age, higher blood CRP, a higher prevalence of CV and non-CV comorbidities and cancer, and a greater risk of death." (PMID 41308509, 2025). "Hs-CRP levels did not predict cancer occurrence, but were significantly associated with 1-year and long-term all-cause mortality." (PMID 40004724, 2025). "CRP and IL-6 levels have been reported to be correlated in many series and different cancer types." (PMID 39754984, 2025). "The C-reactive protein-albumin-lymphocyte (CALLY) index represents a novel composite biomarker that integrates three fundamental aspects of cancer pathophysiology: systemic inflammation (CRP), nutritional status (albumin), and immune function (lymphocyte count)." (PMID 41179090, 2025). "Elevated levels of CRP are commonly observed in patients with cancer." (PMID 39870769, 2025). "In subtype 2, the SHAP importance of ALB was greatest over the 90 days preceding death, and the involvement of inflammatory markers, such as CRP, remained minimal, indicating that the trajectory of subtype 2 represents severe malnutrition or hepatic dysfunction owing to cancer progression." (PMID 40924724, 2025). "Similarly, elevated C-reactive protein levels independently predicted worse survival for individuals with both cancer-specific and relapse-free renal cancer." (PMID 40282466, 2025). "Furthermore, studies demonstrated that cancer patients with elevated CRP concentrations exhibited poorer nutritional status." (PMID 40871652, 2025). "This association may be due to reverse causation, where undiagnosed cancer raises YKL-40 and CRP levels." (PMID 40188292, 2025). "Additionally, the CRP/albumin ratio demonstrated prognostic value in predicting outcomes, especially among patients with malignancies." (PMID 41010574, 2025). "Urban patients receiving regular cancer care had a similar frequency of unplanned inpatient stays (n = 2; 1.0%; p = .219), one due to erysipelas and the other due to elevated CRP levels combined with fever of unknown origin." (PMID 39520275, 2025). "The authors have shown that the connections between IL-6, CRP, and TNF-α and cancer risk may be site-specific." (PMID 40584290, 2025).